LYVE1 (lymphatic vessel endothelial hyaluronan receptor 1)
Diseases named in the same sentence as LYVE1 in open-access papers (continued):
Sharing a sentence is not in itself a finding about the gene and the disease.
Sepsis (5 papers, 2015 to 2024). Sepsis is defined as life-threatening organ dysfunction caused by a dysregulated host response to infection. "The aged mice with SAE showed a significant decrease in the drainage of OVA-647 into the dCLNs and the coverage of the Lyve-1 in the meningeal lymphatic, indicating that sepsis impaired meningeal lymphatic drainage and morphology." (PMID 38287311, 2024). "Western blot analysis revealed that sepsis significantly decreased Lyve-1 and Prox1 levels in the meninges compared to those in the vehicle group, especially at 1 day after LPS injection." (PMID 38287311, 2024). "In the liver, pretreatment with GdCl3 resulted in reduced protein expression of ICAM-1 and its immunoreactivity, which co-localized with LYVE-1 expression in mice with sepsis." (PMID 38254684, 2024). "Our study showed increased ICAM-1 and VCAM-1 immunoreactivity in co-localization with LYVE-1 in a sepsis model." (PMID 37686458, 2023). "In a mouse model where DTR expression is induced in LYVE1+ cells, systemic DT administration depleted LYVE1+ cells in the intestinal–blood barrier, leading to sepsis." (PMID 26441957, 2015). "To investigate whether meningeal lymphatic cells are also damaged by sepsis, we examined the protein levels of Lyve-1, a marker of lymphatic endothelial cells (LECs), and Prox1, a transcription factor that induces lymph angiogenesis, in the meninges." (PMID 38287311, 2024). "In order to better understand the influence of the M18 GAS LYVE-1 interaction on disease outcome and severity, we assessed the impact of LYVE-1 functional blockade on the induction of sepsis in mice following intra-muscular bacterial challenge over a 24 hour period." (PMID 26352587, 2015).
Stroke (5 papers, 2022 to 2025). Sudden impairment of blood flow to a part of the brain due to occlusion or rupture of an artery to the brain. "Our finding indicated that baseline serum CRP, GDNF, IFN-γ, IGFBP-6, IL-4, LYVE-1, MMP-2, PAI-1, and PDGF-AA levels were associated with post-thrombolytic sICH in stroke." (PMID 35173671, 2022). "According to the analysis of meningeal samples from MCAO mice, stroke-induced inflammatory responses or immune cells migration can increase LYVE-1 expression and CD31 endothelial interaction, which was considered an interplay between terminal lymphatic vessels and capillaries." (PMID 40313936, 2025). "However, LYVE-1 MLV coverage and diameter increased at 7 days post-stroke following a single i.c.m. delivery of VEGF-C." (PMID 41099766, 2025).
fibrosis (4 papers, 2021 to 2024). the formation of excess fibrous connective tissue in an organ or tissue in a reparative or reactive process. "In the two fibrosis models, the red fluorescence partially colocalized with LYVE-1 and occurred mostly in the tube-like structures or the neatly arranged cell clusters." (PMID 33479195, 2021). "The result showed that strong colocalization of Lyve-1 and α-SMA/Sm22 was preferentially detected in the sinusoidal but barely in the septal regions (bridging-fibrosis regions) in both CCl4- and BDL-induced fibrosis models." (PMID 34277612, 2021). "Consistent with previous reports 6, 26, the area positive for LYVE-1, an LSEC differentiation marker, was reduced in the liver of alcoholic patients with fibrosis compared with that in healthy controls, whereas the area positive for CD31, a capillary EC marker, was significantly increased." (PMID 38169654, 2024).
hepatocellular carcinoma (4 papers, 2021 to 2025). A malignant tumor that arises from hepatocytes. "Similar to LYVE1, downregulation of LRP1 was also associated with invasiveness and poor prognosis in hepatocellular carcinoma." (PMID 40551123, 2025). "During hepatocellular carcinoma (HCC) progression in humans, LSECs lose the expression of their markers, including lymphatic vessel endothelial hyaluronan receptor-1 (LYVE-1), CD32b, stabilin-1, and stabilin-2." (PMID 40595432, 2025).
liver cancer (4 papers, 2020 to 2025). An epithelial or non-epithelial malignant neoplasm that arises from the liver. "Hyaluronan was shown to induce HepG2 liver cancer cell proliferation, which could also be related to the downregulation of LYVE-1." (PMID 40551123, 2025).
lymphangioma (4 papers, 2007 to 2021). A benign lesion composed of dilated lymphatic channels. "The profile of proteinase expression was different in the L− and L+ macrophage subsets isolated from both cardiac and lymphangioma, thus we examined the effect of macrophage conditioned media (CM) on LYVE-1 protein." (PMID 34413352, 2021). "Lymphatic vessel density in cross-sections of lymphangiomas immunostained for LYVE-1 decreased from approximately 24 to 4 counts/mm2." (PMID 32944404, 2020). "Immunohistochemical analyses of these lymphangiomas were assessed with Lyve-1 and CD45 antibodies to label lymphatic vessels and inflammatory cells, respectively." (PMID 20300183, 2010). "In the lysates prepared from LECs originating from LYVE-1 sorting of HDMECs, VEGFR-3 protein concentrations increased to 19.3 ng/mg, while LECs from lymphangiomas reached values of 29.5 – 40.8 ng/mg, which was significantly higher than the concentrations found in foreskin LECs." (PMID 17584927, 2007). "However, LYVE-1 was down-regulated and VEGFR-2 and R-3 were up-regulated in lymphangiomas." (PMID 17584927, 2007). "However, in contrast to the dermal LECs, LECs from lymphangiomas were either negative for LYVE-1 or expressed this marker only at low levels." (PMID 17584927, 2007).
renal fibrosis (4 papers, 2021 to 2026). A final common manifestation of a wide variety of chronic kidney diseases characterized by glomerulosclerosis and tubulointerstitial fibrosis. "Three renal fibrosis models demonstrated a reduction in full-length LYVE1 and an increase in the soluble LYVE1 fragment." (PMID 41587141, 2026). "While research into increased local renal LYVE1 expression in renal fibrosis has flourished, the literature on the relationship between fibrosis and circulating LYVE1 remains unexplored." (PMID 38135837, 2024). "As the obstruction time increased (7 and 14 days), tubular dilation, degeneration, and atrophy gradually became severe, so it was true for renal fibrosis (Masson, α-SMA), macrophage infiltration (F4/80), and lymphangiogenesis (LYVE-1)." (PMID 33479195, 2021). "Although LYVE1 has been widely used as an LV marker and its increase signifies LVs proliferation, the role of circulating sLYVE1 in renal fibrosis has not been investigated." (PMID 38135837, 2024). "The triple staining results for LYVE-1, α-SMA and collagen I showed that these transformed cells could participate in renal fibrosis through the production of collagen." (PMID 38693148, 2024).
chondrosarcoma (3 papers, 2016 to 2024). A malignant cartilaginous matrix-producing mesenchymal neoplasm arising from the bone and soft tissue. "We also stained for the lymphatic vessel marker (LYVE-1) and found that human chondrosarcoma expressed a higher level of LYVE-1 than normal cartilage." (PMID 38791180, 2024). "Our results revealed that knockdown of WISP-3 inhibited chondrosarcoma-promoted expression of the LEC markers VEGF-C and LYVE-1, indicating that VEGF-C is a critical factor in WISP-3-induced lymphangiogenesis in human chondrosarcoma." (PMID 34680447, 2021). "In the tumor-induced lymphangiogenesis model, the IHC data revealed that knockdown of WISP-3 inhibited chondrosarcoma-promoted expression of WISP-3 and LEC markers VEGF-C and LYVE-1." (PMID 34680447, 2021).
colitis (3 papers, 2018 to 2022). Inflammation of the colon. "COMP-Ang1 also significantly reduced the density of LYVE-1-positive lymphatic vessels and the disruption of colonic architecture that is normally associated with colitis and repressed the immunoregulatory response." (PMID 29610929, 2018). "To investigate the changes in lymphatic density in the DSS-induced colitis model, we performed immunohistochemical staining for LYVE-1, a marker of lymphatic vessel endothelial cells." (PMID 29610929, 2018). "However, LYVE-1 staining indicated that meningeal lymphatic endothelial cells were unaffected by colitis or NLRP3 depletion." (PMID 34229722, 2021). "The density of lymphatic vessel endothelial hyaluronan receptor 1 (LYVE-1) and VEGFR-3-positive lymphatic vessels increased in mice with DSS-induced colitis." (PMID 29610929, 2018).
cutaneous melanoma (3 papers, 2022 to 2024). A primary melanoma arising from atypical melanocytes in the skin. "Here we show that there are at least two subsets of lymphatic vessels in cutaneous melanoma, PDPN+LYVE-1+ and PDPN+LYVE-1-, where LYVE-1 is reported in some cases to correlate with the extent of LN metastasis and overall poor prognosis." (PMID 38361951, 2024). "Lymphatic vessel endothelial hyaluronan receptor-1 (LYVE-1), a selective marker of lymphatic vessels, and D2-40, an endothelial marker known as podoplanin, were used to assess LVI in cutaneous melanomas." (PMID 36613587, 2022). "Liver metastasis as a pathological process was influenced in a tumor-specific fashion as hepatic metastasis of cutaneous melanoma, but not CRC, was reduced upon knockout of Lyve-1." (PMID 36496412, 2022).
heart failure (3 papers, 2012 to 2022). Inability of the heart to pump blood at an adequate rate to meet tissue metabolic requirements. "After 6 weeks of TAC, the number of CD45−CD31+LYVE-1+ lymphatic cells found in the heart was positively correlated with the number of L+ macrophages showing a tight regulation of the lymphatic network during heart failure." (PMID 34413352, 2021).
Lipedema (3 papers, 2019 to 2022). Disorder of adipose tissue characterized by symmetric and bilateral enlargement of the lower extremities due to abnormal deposition of subcutaneous fat often in obese women. "The expression levels of other lymphatic-related genes, such as podoplanin (PDPN), PROX-1, lymphatic-vessel endothelial hyaluronan receptor 1 (LYVE1), and C-C motif chemokine ligand 21 (CCL21), were similar in lipedema fat tissue compared to healthy controls." (PMID 36551837, 2022). "No significant changes were observed for most of the common lymphatic markers, namely PDPN, PROX-1, LYVE-1, CCL21 but a 1.9-fold (P = 0.02) increase was observed in the expression of VEGFR-3 in lipedema in comparison to the control." (PMID 32616854, 2020). "In this regard, three lymphatic vessel markers (podoplanin/PDPN, LYVE-1 and PROX-1) were used to characterize the size and number of lymphatic vessels in paraffin tissue sections from lipedema and control patients." (PMID 32616854, 2020). "Lyve-1 and D2-40 staining showed a significant increase in lymphatic vessel area but not in number or perimeter in Obese Lipedema participants (p < 0.05) compared to Controls (Obese and Non-Obese)." (PMID 30949365, 2019).
neuroblastoma (3 papers, 2020 to 2024). Neuroblastoma (NB) is the most common solid, extracranial childhood tumor. "Increased LYVE-1 expression is associated with lymphatic metastasis and unfavourable prognosis in neuroblastoma." (PMID 38791985, 2024). "Interestingly, in 4 out of 5 specimens, LYVE-1+ vessels were filled with neuroblastoma cells, a vascular feature previously found also in samples from patients." (PMID 33028899, 2020).
primary effusion lymphoma (3 papers, 2012 to 2014). A large B-cell lymphoma located in the body cavities, characterized by pleural, peritoneal, and pericardial fluid lymphomatous effusions and that is always associated with human herpes virus-8 (HHV-8). "CD147 and LYVE-1 may cooperate to regulate chemoresistance in primary effusion lymphoma." (PMID 25268615, 2014).
prostate tumors (3 papers, 2008 to 2025). "Immunostaining for LYVE-1 demonstrated a dense network of lymphatic capillaries in the periphery of tumors as well as in the peritumoral area in our PC-3 prostate tumors." (PMID 18371232, 2008). "Therefore, the expression of CD34 and LYVE-1, markers for vascular and lymphatic vessels, respectively, was also assessed in resected prostate tumors from mice treated with or without 64Cu/NOTA-βAla-R954 using IHC." (PMID 41012550, 2025).
vascular tumors (3 papers, 2010 to 2024). "Furthermore, LYVE-1 can be used to differentiate between benign and malignant vascular tumours, as all angiosarcomas and Kaposi’s sarcoma are positive for LYVE-1." (PMID 38791985, 2024). "Furthermore, strong immunohistochemical expression of antibody against novel lymphatic marker, LYVE-1, might allow discrimination of BL from malignant vascular tumors, although it will be intriguing to see whether LYVE-1 immunoexpression pattern have reliable roles in this regard." (PMID 25358645, 2014). "The specific marker for lymphatic endothelium Lyve-1, a lymphatic vascular endothelial receptor for hyaluronan, was not tested in our patient but has been found also in vascular tumors like Kaposi's sarcoma." (PMID 20170552, 2010).
angiosarcoma (2 papers, 2021 to 2024). A malignant tumor arising from the endothelial cells of the blood vessels. "LAS can be differentiated from other angiosarcomas in dogs based on expression of Prospero-related homeobox gene-1 (PROX-1) or lymphatic vessel endothelial receptor-1 (LYVE-1)." (PMID 34746271, 2021).
autoimmune disease (2 papers, 2017 to 2020). A disorder resulting from loss of function or tissue destruction of an organ or multiple organs, arising from humoral or cellular immune responses of the individual to their own tissue constituents. "Prospective investigation of exosomal levels of AA and LYVE-1 may facilitate development of new diagnostic tools to assess disease activity and prognosis in RA and other autoimmune diseases." (PMID 28569211, 2017). "Few markers with negative correlation have been reported in RA, but exosomal LYVE-1 could be used as an additive marker, with further investigation of the pathogenesis and the mechanism of lymphangiogenesis in RA and autoimmune disease." (PMID 28569211, 2017).
cardiac hypertrophy (2 papers, 2020). "Myocardial edema, stimulated by inflammatory factors during cardiac hypertrophy, may lead to lymph flow dysplasia, abnormal lymphatic genesis, and the increased expression of LYVE-1." (PMID 32420365, 2020).
cervical carcinoma (2 papers, 2010 to 2023). A carcinoma arising from either the exocervical squamous epithelium or the endocervical glandular epithelium. "Intriguingly, LYVE-1 staining showed that the number of lymphatic vessels was robustly increased in intratumoral and peritumoral areas of CCa with low circVPRBP expression, suggesting that circVPRBP may play a vital role in lymphangiogenesis and LN metastasis in cervical cancer." (PMID 36658304, 2023).
endometrial carcinoma (2 papers, 2010). A malignant tumor arising from the epithelium that lines the cavity of the uterine body. "Endometrial carcinoma tissues were analyzed for lymphatic vessels by immunohistochemical staining with an antibody against LYVE-1." (PMID 20374665, 2010). "In this study, LYVE-1 positive vessels were identified as lymphatics in endometrial carcinoma tissue." (PMID 20374665, 2010). "In this study, LYVE-1 staining was used to determine LVD in tissue samples from endometrial carcinoma patients." (PMID 20374665, 2010). "The staining of CD44 was stronger in endometrial carcinoma tissue with LYVE1+ lymphatic vessels than without LYVE1+ lymphatic vessels." (PMID 20374665, 2010). "From a clinical point of view, the analysis of LYVE1 and CD44 expression in endometrial carcinomas may help to identify patients with poor prognosis who may benefit from adjuvant therapies." (PMID 20374665, 2010).
endothelial dysfunction (2 papers, 2021 to 2025). In vascular diseases, endothelial dysfunction is a systemic pathological state of the endothelium (the inner lining of blood vessels) and can be broadly defined as an imbalance between vasodilating and vasoconstricting substances produced by (or acting on) the endothelium. "After alcohol cessation Lyve1 and Stab2 expression returned to control levels, but in contrast, Icam1, Vcam1, and Cd34 stayed elevated or further increased suggesting that endothelial dysfunction persists after alcohol cessation." (PMID 40288442, 2025).
Granuloma (2 papers, 2015 to 2022). A compact, organized collection of mature mononuclear phagocytes, which may be but is not necessarily accompanied by accessory features such as necrosis. "The expression of Lyve-1 in some vessels present in the peripheral zone of mature granulomas suggests the appearance of vessels in this region." (PMID 36091027, 2022). "Furthermore, we identified lymphatic vessels in the peripheral zone of mature granulomas, by immunofluorescence for LYVE-1." (PMID 36091027, 2022). "Additionally, evidence of rare LYVE-1 staining of a lumen containing structure within the granuloma is shown (arrows), and the surrounding area of the granuloma was also positively stained with LYVE-1." (PMID 26279095, 2015).
Hypertension (2 papers, 2020 to 2021). The presence of chronic increased pressure in the systemic arterial system. "Western blot and RT‐PCR demonstrated that the mRNA and protein level of VEGFR3 and LYVE1 were down‐regulated in heart of hypertension mice compared with saline group, and SIRT3‐KO further down‐regulated the mRNA and protein expression in hypertension model." (PMID 34180125, 2021). "Angiotensin II infusion significantly increased the mRNA expression levels of lymphatic endothelial markers Lyve1, Pdpn, Vegfc, and Flt4 in kidney, which is consistent with previous reports and represents an endogenous expansion in response to systemic hypertension." (PMID 33200983, 2020).
hypertrophic cardiomyopathy (2 papers, 2020 to 2022). A condition in which the myocardium is hypertrophied without an obvious cause. "LCZ696 also decreased the protein expression levels of VEGF-C, VEGFR3, and LYVE-1 in mouse heart tissues, ameliorated the transport load of lymphatic vessels to macrophages, and improved the remodeling of the lymphatic system in the hypertrophic cardiomyopathy model induced by TAC." (PMID 32420365, 2020).
insulinoma (2 papers, 2012 to 2014). "It was reported that in mouse models of pancreatic insulinoma and prostate cancer F4/80+Lyve-1+ TAM directly integrated into peritumoral lymphatic vessels and presumably lost their macrophage features upon this integration." (PMID 24634660, 2014). "Moreover, our examination of the TAM phenotype in pancreatic insulinoma and melanoma mouse models demonstrated that LYVE-1 can be expressed not only by lymphatic vessels, but also by TAM themselves." (PMID 24634660, 2014). "In the model of Rip1/Tag2 insulinoma, adoptively transferred GFP-tagged BM-derived LECP were detected in 3–4% of Prox1+, LYVE-1+, or podoplanin+ peritumoral lymphatic vessels." (PMID 22946011, 2012).
ischemia (2 papers, 2012 to 2019). A hypoperfusion of the BLOOD through an organ or tissue caused by a PATHOLOGIC CONSTRICTION or obstruction of its BLOOD VESSELS, or an absence of BLOOD CIRCULATION. "Second, our mouse model of focal ischemia showed rapid LYVE-1 upregulation in CLNs that may represent lymphangiogenesis and lymphatic endothelial proliferation." (PMID 31757960, 2019). "Double-staining using LYVE-1 and Ki67 antibodies confirmed that lymphatic endothelium in the area of subcapsular sinus in superficial CLNs were increased as early as 3 h after focal ischemia, and the lymphatic response in superficial CLNs was sustained until 24 h after focal ischemia." (PMID 31757960, 2019).
lung fibrosis (2 papers, 2022 to 2025). "LYVE1+ Mφ regulates tissue homeostasis by suppressing lung fibrosis and maintaining arterial vessels in the heart." (PMID 40874258, 2025).